STAT3 (signal transducer and activator of transcription 3)
Diseases named in the same sentence as STAT3 in open-access papers (continued):
Sharing a sentence is not in itself a finding about the gene and the disease.
cardiac hypertrophy (continued). "Thus, loss of STAT3 and its input into cardiac hypertrophy would be compensated for by activation of this pathway." (PMID 30619368, 2018). "STAT3 mediated by IL-6 is another major cause to cardiac hypertrophy." (PMID 25122164, 2014). "Moreover, we determined the importance of leptin-mediated STAT3 activation for the development of cardiac hypertrophy in obesity by analyzing mice with targeted mutation of the STAT3 binding site within LepR." (PMID 23841921, 2013). "Therefore, we assessed whether miR-320 is involved in cardiac fibrosis’s pathophysiology and the molecular mechanism of miR-320 underlying STAT3 on cardiac hypertrophy and fibrosis using human serum samples and hypertrophic mice models." (PMID 34582362, 2021). "Importantly, STAT3 signalling has been associated with the regulation of cardiac hypertrophy with reports suggesting that overactivation of STAT3 might result in an overt hypertrophic response." (PMID 27693579, 2016). "In angiotensin II type 1 receptor-induced (AT1R) cardiac hypertrophy, U-STAT3 accumulates in nucleus in response to unregulated STAT3 expression due to chronic activation of AT1R." (PMID 40725945, 2025). "CHACR attenuated cardiac hypertrophy by increasing the expression of CPT1b, which is involved in regulation of the Jak2/Stat3 pathway, demonstrating the participation of this circRNA-mediated protein mechanism in the pathogenesis of cardiac hypertrophy." (PMID 40093901, 2025). "Inhibition of STAT3 abolished the cardioprotective effects of YOD1CKO in Ang II–infused mice, validating the YOD1-STAT3 axis in regulating cardiac hypertrophy." (PMID 40561034, 2025). "Murine models with cardiac-specific deletion of STAT3 (conditional knockout, cKO) develop cardiac hypertrophy and HF in the peripartum period." (PMID 40868277, 2025). "This study delves into the role of YAP in ISO-induced cardiac hypertrophy and how it exerts this effect through the regulation of the IL-6/STAT3 signaling pathway in CFs." (PMID 40919415, 2025). "Emerging evidence highlights that aberrant activation of the STAT3 signaling plays a critical role in both cardiac hypertrophy and cancer progression, acting as a shared driver of the pathological processes in HF and tumorigenesis." (PMID 40924729, 2025). "Previous studies have demonstrated that the inhibition of STAT3 signaling, either through Stattic or siRNA knockdown, can significantly ameliorate cardiac hypertrophy." (PMID 40561034, 2025). "Cardiomyocyte‐enriched USP20 regulates the K63‐linked ubiquitination of STAT3, and the cardiomyocyte‐specific USP20‐STAT3‐CARM1 axis exerts a protective role in cardiac hypertrophy." (PMID 40192103, 2025). "On this foundation, we proved that CPT1b suppressed Jak2/Stat3 signaling pathway to aggravate cardiac hypertrophy." (PMID 40093901, 2025). "Collectively, we showed that cardiomyocyte YOD1 deubiquitinates and stabilizes STAT3 to drive cardiac hypertrophy, fibrosis, and dysfunction." (PMID 40561034, 2025). "Our data suggested that STAT3 is vital for the regulatory function of ECSIT‐X4 on pressure overload‐induced cardiac hypertrophy." (PMID 39746855, 2025). "The activity of Stat3 is strictly regulated in physiological processes, and its abnormal and persistent activation leads to pathological cardiac hypertrophy 34,35." (PMID 40093901, 2025). "CHACR, which was mainly expressed in the cytoplasm, bound directly to CPT1b and upregulated its expression, which consequently inhibited L-carnitine level to inactivate the Jak2/Stat3 pathway, thereby attenuating cardiac hypertrophy (Graphical abstract)." (PMID 40093901, 2025). "Our findings demonstrated that verteporfin protects the heart from ISO-induced myocardial hypertrophy through mechanisms involving the regulation of the IL-6/STAT3 pathway in cardiac fibroblasts (CFs)." (PMID 40919415, 2025). "Among these nine, only STAT3 has been reported to play an essential role in the progression of pathological cardiac hypertrophy." (PMID 40561034, 2025).
cardiac hypertrophy (continued). "We demonstrated the novel role of ECSIT‐X4 in mitigating pressure overload‐induced pathological cardiac hypertrophy by interacting with and regulating mitochondrial STAT3, thereby modulating OXPHOS function." (PMID 39746855, 2025). "Cardiac single-nucleus RNA sequencing of the hearts and in vitro analysis of the cardiomyocytes indicated up-regulation of the STAT3 signal transduction pathway as a potential contributor of VEGFB-induced cardiac hypertrophy." (PMID 40116846, 2025). "We engineered AAV9 viral vectors controlled by the cardiomyocyte‐specific cTnT promoter to knock down Stat3 in cardiomyocytes and determined its role in improving cardiac hypertrophy mediated by ECSIT‐X4 in vivo." (PMID 39746855, 2025). "Upon its translocation to the nucleus, STAT3 binds to specific promoters, leading to the transcription of target genes that facilitate cardiac hypertrophy." (PMID 40561034, 2025). "Collectively, this study has unveiled a novel molecular mechanism involving the interaction between ECSIT‐X4 and STAT3 within mitochondria, which serves to mitigate energy deficits in hypertrophic cardiomyocytes and pathological cardiac hypertrophy." (PMID 39746855, 2025). "For instance, inhibition of STAT3 Y705 phosphorylation was shown to significantly enhance cardiac function in a rat model of stress-induced cardiac hypertrophy." (PMID 39200351, 2024). "Myocardial hypertrophy was observed in transgenic mice with cardiac-specific overexpression of STAT3, leading to increased expression of cardiotrophin‐1, α‐myosin heavy chain (MHC), and atrial natriuretic factor (ANF;)." (PMID 39455447, 2024). "A number of studies have shown that inhibition of cardiac hypertrophy and remodelling in different experimental models is associated with inhibition of JAK2/STAT3 activity." (PMID 38256208, 2024). "Exosomal Hsp90 derived from cardiomyocytes, along with secreted IL-6, participates in the activation of STAT-3 signaling within cardiac fibroblasts, leading to enhanced synthesis and accumulation of collagen during cardiac hypertrophy." (PMID 39850481, 2024). "It was later found that STAT3 activation also plays a role in cardiac remodeling, where the protein is an important modulator of ventricular hypertrophy and regeneration." (PMID 39455447, 2024). "Meanwhile, the NF-κB pathway and the JAK/STAT3 pathway, in which Toll-like receptor 4 is involved, are thought to be involved in cardiac hypertrophy." (PMID 38402404, 2024). "Phosphorylated STAT3 forms homo/heterodimers and translocates from the cytoplasm into the nucleus, through which the transcription of downstream genes related to cardiac hypertrophy is activated." (PMID 37120549, 2023). "Cardiac hypertrophy and fibrosis are associated with the activation of the JAK2/STAT3 signaling pathway." (PMID 36671504, 2023). "In summary, the present study shows for the first time that OSMR deficiency exerts adverse effects on the development of pressure overload-induced cardiac hypertrophy, which is mediated by OSM/LIFR/STAT3 signalling associated with macrophages and inflammation." (PMID 37120549, 2023). "The progression of cardiac hypertrophy is also associated with dysregulated IGF signaling, intracellular NAD levels, activation of autophagy, as well as upregulation of signal transducer and activator of transcription 3 (STAT3)." (PMID 37497437, 2023). "To investigate the mechanism of the effects of rhein on cardiac hypertrophy, we examined its effects on STAT3 and P38/MAPK signaling in AngII-induced hypertrophy and proliferation of H9C2 and AC16 cells." (PMID 36091816, 2022). "On the other hand, STAT3 participates in pathological mechanisms contributing to cardiac hypertrophy, cardiac fibrosis, and septic cardiomyopathy by promoting the growth of cardiomyocytes, collagen synthesis, and the progress of inflammation." (PMID 36148063, 2022).
cardiac hypertrophy (continued). "Continuous STAT3 activation (tyrosine 705 residue phosphorylation) was regarded as a poor indicator in cardiac hypertrophy and heart failure." (PMID 36291052, 2022). "Nrf2 transcription factor deficiency has been reported to induce oxidative stress, inflammation, cardiac hypertrophy/fibrosis and further dysfunction via the IL-6/STAT3 axis." (PMID 36012897, 2022). "Numerous studies have shown that the JAK2/STAT3 signalling pathway is a key signal transduction pathway known to participate in the progression of cardiac hypertrophy." (PMID 35365949, 2022). "CHR alleviates isoproterenepin-induced cardiac hypertrophy by repressing JAK2/STAT3 pathway activation." (PMID 35599576, 2022). "Based on these results, we conclude that rhein can be targeted to alleviate TAC operation- and AngII-induced cardiac hypertrophy by inhibiting the STAT3 and P38/MAPK signaling pathways." (PMID 36091816, 2022). "Modern pharmacological studies have established that the JAK2/STAT3 signalling pathway participates in the progression of myocardial ischaemia, cardiac hypertrophy and heart failure." (PMID 35365949, 2022). "Enrichment of the STAT3 pathway has been shown to promote cardiac hypertrophy by inducing the growth of CMs." (PMID 35207580, 2022). "The JAK2/STAT3 signaling pathway is a common signal transduction pathway in the development of HF and plays a crucial role in myocardial hypertrophy." (PMID 36670950, 2022). "39sahnchuConversely, other studies have also pointed out STAT3 drives cardiac hypertrophy and heart failure by impairing mitochondrial bioenergetics, and STAT3 induces cardiac fibroblast activation and cardiac fibrosis." (PMID 36160853, 2022). "Collectively, our data reveals a therapeutic property of pirfenidone on ISO-induced cardiac hypertrophy in mice via inhibition of the JAK2/STAT3 pathway." (PMID 35609321, 2022). "FNDC5 deficiency promotes high-cholesterol-diet-induced cardiac hypertrophy, elevated inflammatory cytokine expression and oxidative stress via the JAK2/STAT3 pathway." (PMID 36012897, 2022). "Protocatechuic aldehyde protects against ISO-induced cardiac hypertrophy via inhibition of the JAK2/STAT3 signaling pathway." (PMID 36670950, 2022). "Collectively, these findings suggested that PM improved AngII‐mediated cardiac hypertrophy by modulating STAT3." (PMID 35365949, 2022). "Among these pathways, STAT3 is reported to be critical to cardiac fibrosis and hypertrophy and activated in the hearts of mouse models of cardiac hypertrophy and heart failure." (PMID 36291052, 2022). "Recent research has revealed that cardiac hypertrophy can be effectively improved by inhibiting the activation of the JAK/STAT3 signalling pathway using STAT3 inhibitors or silencing the STAT3 gene." (PMID 35365949, 2022). "Many studies have demonstrated that Bmx can reduce the occurrence of cardiac hypertrophy, acting through the coronary endothelium and STAT3." (PMID 35296647, 2022). "MiR-361-5p directly targets recombinant histone deacetylase 9 (HDAC9), and thus STAT3 promotes cardiac hypertrophy." (PMID 36148063, 2022). "In response to numerous cytokines and chemokines, STAT3 converges multiple signal transduction pathways and contributes to myocardial remodeling and fibrosis in cardiac hypertrophy." (PMID 34790705, 2021). "STAT3 has been demonstrated to play roles in several cardiovascular diseases, including MI, arteriosclerosis, cardiac hypertrophy, and heart failure." (PMID 34194542, 2021). "Regarding STAT3's role in mitochondrial regulation of cardiac hypertrophy, it protects mitochondria indirectly via upregulation of the anti-apoptotic proteins, such as Bcl2." (PMID 34642818, 2021). "For instance, JAK2/STAT3 and nuclear factor-κB (NF-κB) signaling pathways are closely involved in the development of cardiac hypertrophy." (PMID 34194329, 2021).
cardiac hypertrophy (continued). "Among them, JAK2 and STAT3 have been attracted our attention because the JAK2/STAT3 pathway is closely related to myocardial hypertrophy and fibrosis." (PMID 34764873, 2021). "The results implied that STAT3 was involved in miR-320 mimics-induced cardiac hypertrophy and fibrosis." (PMID 34582362, 2021). "Based on these results, we conclude that loganin mitigates Ang II–induced cardiac hypertrophy at least partially through inhibiting the JAK2/STAT3 and NF-κB signaling pathways." (PMID 34194329, 2021). "Based on these results, we concluded that loganin mitigated Ang II–provoked cardiac hypertrophy at least partially through inhibiting the JAK2/STAT3 and NF-κB signaling pathways." (PMID 34194329, 2021). "Studies have found that STAT3 activation occurs in cardiac hypertrophy and is involved in cell growth." (PMID 34221090, 2021). "The latest research found that the JAK2/STAT3 pathway participates in the process of AngII-induced myocardial remodeling by promoting myocardial hypertrophy and fibrosis." (PMID 34764873, 2021). "According to the study of Ricke‐Hoch, pregnant mice with a cardiomyocyte‐restricted deletion of Stat3 display cardiac hypertrophy, lower capillary density and increased cathepsin D activity." (PMID 32529705, 2020). "Our data established that cardiomyocyte-specific deletion of STAT3 in mice would lead to cardiac fibrosis, decreased capillary density, cardiac hypertrophy, and eventually impaired cardiac diastolic function partly by reducing the levels of PKG." (PMID 33365331, 2020). "STAT3, as a multifaceted molecule, plays a central role in organic fibrogenesis and cardiac hypertrophy." (PMID 31934850, 2020). "Inhibition of STAT3 induced down-regulation of collagen synthesis and regression of hypertrophy, suggesting that STAT3 is a major potential therapeutic target for cardiac hypertrophy." (PMID 31709266, 2019). "Other studies have demonstrated that persistent STAT3 activation promotes uncontrolled growth and survival through altered gene expression, leading to pathologic cardiac hypertrophy." (PMID 31360296, 2019). "Through these varied roles, STAT3 participates in various mechanisms that contribute to cardioprotection against different heart pathologies, including myocardial infarction, hypertrophy, diabetic cardiomyopathy, and peripartum cardiomyopathy." (PMID 31709266, 2019). "All our findings revealed that STAT3-inducetd upregulation of lncRNA MEG3 controls cardiac hypertrophy by regulating miR-362-5p/HDAC9 axis." (PMID 30679521, 2019). "Signal transducer and activator of transcription 3 (STAT3) is an important transcriptional factor that regulates cell proliferation, apoptosis, and cardiac hypertrophy." (PMID 31360296, 2019). "FNDC5 ameliorated HFD-induced cardiac hypertrophy, via the effects on inflammation, oxidative stress and NFκB activation, in association with JAK2/STAT3 signaling inhibition." (PMID 30940158, 2019). "Increasing evidence suggests that the JAK2/STAT3 pathway is involved in the development of cardiac hypertrophy." (PMID 30940158, 2019). "Growing evidence points to the regulatory capacity of JAK2/STAT3 pathway on inflammation-related diseases and cardiac hypertrophy." (PMID 30940158, 2019). "Next, AngII induced cardiac remodeling and increased the levels of phospho-p38, phospho-JNK, and phospho-STAT3, which are important members of pathways regulating cardiac hypertrophy and apoptosis, while Arsb overexpression inhibited the increase in NMVMs." (PMID 31612078, 2019). "In the present review, we focus on recent developments addressing the importance of STAT3 in cardiac hypertrophy, myocardial infarction (MI), heart failure, and peripartum cardiomyopathy, with particular focus on the contribution of immunity and inflammation." (PMID 30619368, 2018).
cardiac hypertrophy (continued). "Others have recently reported that endogenous activation of the oxoglutarate receptor 1 (OXGR1) during pressure overload from TAC attenuated cardiac hypertrophy in the mouse by suppressing STAT3 activity." (PMID 30619368, 2018). "Given the importance of oxidative stress in the pathogenesis of cardiac hypertrophy and heart failure, it seems likely that STAT3 redox signaling has functional ramifications under these conditions." (PMID 30619368, 2018). "Although early studies showed that transgenic overexpression of STAT3 in mouse hearts induced pathological cardiac hypertrophy, the role of this transcription factor in hypertension-induced cardiac remodeling is still unsettled." (PMID 30619368, 2018). "The vast majority of studies have indicated that the excessive activation of the STAT3 pathway promotes cardiac hypertrophy." (PMID 29358851, 2017). "Previous reports have also suggested that JAK2/STAT3 promoted the transition of cardiac hypertrophy to failure." (PMID 28686615, 2017). "Signal transducers and activators of transcription 3 (STAT3) is known to participate in various cardiovascular signal transduction pathways, including those responsible for cardiac hypertrophy and cytoprotection." (PMID 28686615, 2017). "The conclusion the STAT3 couples to cardiac hypertrophy is largely based on circumstantial evidence obtained using cells in culture; definitive evidence that endogenous STAT3 is essential for physiological or pathological hypertrophy of the heart is lacking." (PMID 27899891, 2016). "NF-κB and STAT3 are signal transduction factors that are important in promoting ventricular hypertrophy." (PMID 27000070, 2016). "As reported in several studies, signal transducer and activator of transcription 3 (Stat3) pathway is another signaling cascade that plays a major role in the development of cardiac hypertrophy." (PMID 27190998, 2016). "Cardiac hypertrophy was enhanced by STAT3 ablation after MI and consequently capillary density was reduced in the border zone." (PMID 26664907, 2015). "This conclusion has been supported by previous studies showing that STAT3 activation is involved in the development of cardiac hypertrophy 40–43." (PMID 25583328, 2015). "Our results have also suggested a role of the STAT3/c-Myc pathway in miR-16 down-regulation during cardiac hypertrophy." (PMID 25583328, 2015). "Previous studies also showed that ROS activate Jak2 and thereafter STAT3 involved in cardiac hypertrophy." (PMID 25247053, 2014). "During cardiac hypertrophy and heart failure, STAT3 signaling contributes to cardioprotection by promoting cardiomyocyte survival via the interleukin (IL)-6/STAT3 axis and transcriptional regulation." (PMID 22418922, 2012). "Additionally, ALKBH5 mediates the demethylation of STAT3 and regulates the expression of inflammatory factors (such as IL-6 and TNF-α) by activating the JAK2/STAT3 signaling pathway, thereby affecting the progression of cardiac hypertrophy." (PMID 40290189, 2025). "Inhibition of STAT3 leads to regression of the hypertrophic pathologies in the heart, whereas cardiac hypertrophic responses are noted as a result of overexpression of STAT3 in cardiomyocytes in vivo, supporting cell-autonomous effects of activated STAT3 in cardiac hypertrophy." (PMID 40028160, 2025). "To assess whether USP20 can improve cardiac hypertrophy by regulating STAT3, we administered wild type and USP20 CKO mice with or without STAT3 inhibitor stattic (10mg kg−1, i.g.)." (PMID 40192103, 2025). "In the context of cardiac hypertrophy, inhibition of STAT3 signaling is generally protective, suggesting antagonizing JAK1 signaling in adulthood may even be antihypertrophic and cardioprotective." (PMID 40744288, 2025). "Therefore, we focused on Jak2/Stat3 signaling pathway, which was a vital signaling pathway involved in cardiac hypertrophy." (PMID 40093901, 2025).